SLCO1B1 (solute carrier organic anion transporter family member 1B1)
Diseases named in the same sentence as SLCO1B1 in open-access papers (continued):
Sharing a sentence is not in itself a finding about the gene and the disease.
myopathy (continued). "For example, the presence of 512C>T variant in SLCO1B1 gene (rs4149056) corresponds with decreased clearance of methotrexate and occurrence of statin-induced myopathy." (PMID 32474888, 2020). "The two SNPs that seem to be strongly associated with statin myopathy in the discovery and replication cohorts are within two gene loci (SLCO1B1 and SLCO1A2) that are in a strong block of linkage disequilibrium in the discovery cohort (data not shown)." (PMID 31220337, 2019). "The data highlight the role of SLCO1B1 c.521C>T SNP as a replicable genetic risk factor for statin myopathy." (PMID 31220337, 2019). "Variants in SLCO1B1 associated with breast cancer risk and statin‐induced myopathy in postmenopausal women using oral conjugated equine estrogen with medroxyprogesterone acetate." (PMID 31844524, 2019). "Pharmacogenomic research has indicated that SLCO1B1*5 can reduce hepatic uptake and increase statin concentrations, leading to an increased risk of simvastatin-induced myopathy." (PMID 30936830, 2019). "Sensitivity analysis of discovery cases (all myopathy) for simvastatin cases only showed no genomewide significant association signals (P > 5 × 10−8), although SLCO1B1 was among the top associated loci." (PMID 31220337, 2019). "For a number of years, the c.521T>C SLCO1B1 variant has been recognized as a clinically important risk factor for statin‐induced myopathy, particularly with regard to simvastatin, and to a lesser extent atorvastatin." (PMID 31220337, 2019). "In vivo, the SLCO1B1 c.521T>C polymorphism is associated with increased risk of simvastatin-induced myopathy." (PMID 29538325, 2018). "In contrast, the G allele in the A388G SNP of the SLCO1B1 gene results in a lower risk of statin-induced myopathy." (PMID 29296187, 2017). "In patients with the C allele at the SNP rs4149056 in the SLCO1B1 gene, there are modest increases in myopathy risk even at lower doses of simvastatin (40 mg daily); if optimal efficacy is not achieved with a lower dose, alternate agents should be considered." (PMID 26785747, 2016). "We performed this meta-analysis to provide a more comprehensive estimation of the association between the two SNPs, SLCO1B1 −521T>C and −388A>G polymorphisms and statin-induced various ADRs not only myopathy, under various genetic models." (PMID 27606156, 2016). "In a genome-wide study the SEARCH Collaborative Group has identified the rs4149056 C allele in SLCO1B1 as being strongly associated with an increased risk of statin-induced myopathy." (PMID 27234217, 2016). "The finding led the group to further sequencing of other regions on SLCO1B1 and resulted in the identification of several other common variants of the gene that were strongly associated with statin-induced myopathy." (PMID 27708556, 2016). "Recent studies showed that genetic variants in the SLCO1B1 gene modified the risk of statin-induced myopathy, but the results were controversial." (PMID 27606156, 2016). "Case-control studies investigating the association between SLCO1B1 gene T521C polymorphism and statin-related myopathy risk were included." (PMID 26376374, 2015). "The available evidence suggests that SLCO1B1 gene T521C polymorphism is associated with an increased risk of statin-related myopathy, especially in individuals receiving simvastatin." (PMID 26376374, 2015). "The evidence of association between solute carrier organic anion transporter 1B1 (SLCO1B1) gene T521C polymorphism and statin-related myopathy risk remained controversial." (PMID 26376374, 2015). "Although a number of studies have reported the association of SLCO1B1 gene T521C polymorphism and statin-related myopathy risk, considerable discrepancies among them have made the real relationship vague." (PMID 26376374, 2015). "In conclusion, we found a significant association between SLCO1B1 gene T521C polymorphism and statin-related myopathy risk, especially in patients taking simvastatin." (PMID 26376374, 2015).
myopathy (continued). "There is a heritable component to the risk for statin-induced myopathy and the role for PGx testing in guiding statin pharmacotherapy is evolving, particularly for the solute carrier organic anion transporter family, member 1B1 (SLCO1B1) gene." (PMID 26030725, 2015). "Recently, some studies have clarified the association between the polymorphisms of solute carrier organic anion transporter 1B1 (SLCO1B1) gene and statin-related myopathy risk." (PMID 26376374, 2015). "Extensive literature and FDA warning labels indicate increased risk for myopathy in patients with specific genetic differences on the SLCO1B1 gene." (PMID 26334733, 2015). "Another recent discovery found the C variant of the rs4363657 polymorphism of SLCO1B1 gene strongly associated with statin induced myopathy in more than 60 % of cases." (PMID 26334733, 2015). "In a GWAS of the genetic risk factors for simvastatin-induced myopathy, SLCO1B1 showed the strongest association." (PMID 25350695, 2014). "For simvastatin, based on the currently available data, it seems unlikely that pharmacokinetic genes other than SLCO1B1 will be clinically important for predicting risk of simvastatin-induced myopathy." (PMID 25221728, 2014). "There is a need for studies comparing the clinical validity of SLCO1B1 rs4149056 genotyping with risk scores for myopathy based on other factors such as racial background, statin type and dose, gender, body mass index, co-medications and co-morbidities." (PMID 24459608, 2013). "The myopathy risk associated with SLCO1B1 was first reported in a study reported by the Study of the Effectiveness of Additional Reductions in Cholesterol and Homocysteine (SEARCH) Collaborative Group." (PMID 25562358, 2012). "Clinical evidence shows a strong association between carriage of alleles of SLCO1B1 and both mild myalgia and clinically severe myopathy." (PMID 25562358, 2012). "Recent studies reported the association between SLCO1B1 polymorphisms and the development of statin-induced myopathy." (PMID 21992719, 2011). "The main finding of the present study was to observe significant differences between the allelic and genotypic frequencies of SLCO1B1 rs4149056 polymorphism associated with statin-induced myopathy, according to ethnicity in the Brazilian general population." (PMID 21992719, 2011). "Similarly, SLCO1B1 genotyping to assess statin uptake canpredict risk of myopathy and enable dose adjustments or drug substitution to improve tolerability." (PMID 41170027, 2025). "Anti-lipids: SLCO1B1 variants (e.g., rs4149056) increase statin-induced myopathy risk." (PMID 40724525, 2025). "A decreased OAPT1B1 function because of the SLCO1B1 c.521T>C variant leads to increased systemic and reduced hepatic statin concentrations; it is strongly related to the risk of myopathy (odds ratio of 4.5 per copy of C allele), and—to a lesser extent—to the LDL-C-lowering effect." (PMID 39861708, 2025). "Although SLCO1B1is not a gene from the cytochrome P450 system, evidence clearly indicates that polymorphisms in the SLCO1B1 genotype affect statin pharmacokinetics and may increase the risk of myopathy in some patients." (PMID 40193664, 2025). "Polymorphism of c.521T > C, p.Val174Ala in the SLCO1B1 gene encoding OATP1B1 reduced the ability of OATP1B1 to transport active simvastatin acid from the bloodstream into the liver, and thereby enhanced the risk of statin-induced myopathy." (PMID 38204221, 2024). "The C, or minor allele of this locus has been associated with a decrease in the SLCO1B1 transporter function resulting in reduced clearance of several drugs in vivo and clearly links the SLCO1B1*5, *15 and *17 haplotypes with simvastatin-induced myopathy." (PMID 38523294, 2024). "Additionally, the risk of myopathy increases by 2.6 and 4.3 per copy of SLCO1B1*5 in patients, respectively, on simvastatin 40 mg and 80 mg daily." (PMID 38550953, 2023).
myopathy (continued). "Moreover, SLCO1B1 variants were associated with severe forms of myopathy and rhabdomyolysis with levels of CK >10x ULN." (PMID 37206522, 2023). "Our findings further supported the role of the SLCO1B1 genotype in statin-associated myopathy and suggested that this association may be more robust for atorvastatin and simvastatin." (PMID 33608664, 2021). "Two polymorphisms (rs2306283 and rs4149056) of SLCO1B1 gene have been reported that they could influence statin and the risk of myopathy association." (PMID 33608664, 2021). "Two polymorphisms (rs2306283 and rs4149056) of SLCO1B1 gene have been reportedly associated with statin and risk of myopathy in statin users, as it could influence the plasma concentration of statins." (PMID 33608664, 2021). "Also, SLCO1B1*15 showed over 70% reduction in the transport activity compared with wild type and showed the association with myopathy in patients taking pravastatin and atorvastatin." (PMID 32581780, 2020). "Additionally, mutations in the SLCO1B1 gene are particularly known to predispose to statin-induced myopathy." (PMID 29763460, 2018). "SNPs related to myopathy, like the SLCO1B1, ABCB1, and ABCG2 gene polymorphisms, could be taken into account when considering combined treatment with statins." (PMID 30050433, 2018). "In summary, we have demonstrated that SLCO1B1 gene T521C polymorphism is significantly associated with statin-related myopathy, the variant C allele may increase the risk of developing statin-related myopathy (especially severe myopathy)." (PMID 26376374, 2015). "SLCO1B1 is a marker for statin safety and may be capable of personalizing treatment to a patient’s individual risk of myopathy, an independent barrier to optimal adherence." (PMID 25562358, 2012). "Since there is a gradient of effect for variations in this transporter across the statin class, it may be possible to personalize statin treatment for the patient’s effectiveness goals as well as their predisposition to myopathy according to SLCO1B1 genotype." (PMID 25562358, 2012). "The SLCO1B1 transporter is of particular interest because it is known to transport simvastatin from plasma into the liver, and SNP rs4149056 has been associated with statin-induced myopathy in individuals treated with high dose simvastatin." (PMID 22022402, 2011). "Furthermore, SLCO1B1*5 is strongly associated with myopathy among simvastatin users." (PMID 36050458, 2022). "The risk of myopathy may be partly explained by a genetic variation in the SLCO1B1 gene." (PMID 34834533, 2021). "Given that all types of statins were substrates of OATP1B1 transporter, we would need more genetic association studies of the SLCO1B1 gene and myopathy among other types of statin to confirm that the effects could be a class effect or specific types of statin only." (PMID 33608664, 2021). "If simvastatin is prescribed to a patient with intermediate SLCO1B1 function as a heterozygous variant, there is an increased risk for developing simvastatin-associated myopathy; such cases might require a lower starting dose of simvastatin or another statin agent." (PMID 33505429, 2020). "Furthermore, it could be of value to investigate whether an individual is predisposed to higher circulating statin concentrations, and thus a higher risk of myopathy, due to variation in the known susceptibility gene SLCO1B1." (PMID 30618488, 2018). "More importantly, the results of our study may serve as evidence for guiding the preemptive SLCO1B1 testing by identifying individuals with high risk of simvastatin-related myopathy and thereby optimizing the statin therapy to avoid drug-related myopathy and promote a stronger adherence." (PMID 26376374, 2015). "The authors of this GWAS plus replication study concluded that common variants in the SLCO1B1 gene are strongly associated with an increased risk of statin-induced myopathy and genotyping may help to obtain benefits of statin therapy more safely and effectively." (PMID 21992719, 2011).
myopathy (continued). "For instance, mutations in SLCO1B1, which encodes the organic anion-transporting polypeptide 1B1 (OATP1B1), have been linked to increased statin-induced myopathy, demonstrating how transporter polymorphisms can impact drug disposition and toxicity." (PMID 40430848, 2025). "In previous studies, the genetic variants of SLCO1B1 were proven to be relevant to the response to drugs transported by OATP1B1, such as statin-induced myopathy, irinotecan-induced toxicities, methotrexate clearance." (PMID 39295941, 2024). "The SNP rs4149056 T>C in the SLCO1B1 locus, also known as Val174Ala or SLCO1B1*5, which has previously been associated with LDL-C statin response as well as clinical myopathy barely missed genome-wide significance level (beta = −0.063, p-value = 5.33e-08)." (PMID 38633781, 2024). "The clinical importance of SLCO1B1, mainly *5 or *15, for statin-induced myopathy is well demonstrated." (PMID 36478296, 2023). "Decreased transporter activity due to SNPs in SLCO1B1 is recognized as an important factor in statin-related ADRs, namely myopathy." (PMID 37686303, 2023). "The Clinical Pharmacogenomics Implementation Consortium Guidelines for SLCO1B1 and Simvastatin-induced Myopathy provide a decision support algorithm for prescribing simvastatin to patients with SLCO1B1*5 genotype." (PMID 34749751, 2021). "An association between the genetic variation of SLCO1B1 gene and SIM was initially discovered by a GWAS comprising of 85 participants with suspected simvastatin-myopathy and 90 matched controls." (PMID 33193687, 2020). "Both rs4149056 in SLCO1B1 and rs4149000 in SLCO1A2 were significantly associated with both definite myopathy (P = 7.30 × 10−14 and P = 7.62 × 10−11, respectively) and the incipient or definite myopathy phenotype (P = 1.33 × 10−11 and 6.49 × 10−12)." (PMID 31220337, 2019). "The relationship between cerivastatin and SLCO1B1 (off-target) that was uncovered in an internal database provided the link to the direct connection between SLCO1B1 and myopathy curated within CTD." (PMID 27161010, 2016). "The data to support SLCO1B1 variation and simvastatin-induced myopathy was sufficiently strong to incite CPIC to write guidelines on the translation of SLCO1B1 genotype into the clinical use of simvastatin." (PMID 25221728, 2014). "Solute carrier organic anion transporter family member 1B1 (SLCO1B1) is a predictive marker of statin-related myopathy (SRM) which is a significant barrier to optimal adherence." (PMID 25562358, 2012). "A Pubmed search using the terms simvastatin AND SLCO1B1 AND Brazil* disclosed no studies of association of SLCO1B1 variants with simvastatin‐induced myopathy." (PMID 41016862, 2026). "Variants in SLCO1B1, ABCG2, and CYP2C9 were combined into a functional PGx burden score, and their associations with statin regimen modification, intolerance, myopathy, liver injury, adherence, and composite adverse events were evaluated." (PMID 41901359, 2026). "For instance, one study found that single nucleotide polymorphisms such as c.521T > C in the SLCO1B1 gene, which encodes OATP1B1, were associated with a 2-fold increase in risk of all myopathies and was also shown to be significantly associated with simvastatin-induced myopathies." (PMID 40149400, 2025). "Moreover, pharmacogenomic insights exemplified by CYP2C19 genotyping to guide clopidogreland SLCO1B1 testing to mitigate statin-induced myopathy have demonstrated the capacity to reduce adverse events and optimize drug efficacyin routine practice." (PMID 41170027, 2025). "The multispecific hepatic “drug” transporter OATP1B1 (SLCO1B1), associated with statin myopathy, also had several associations with a wide array of small molecules, including eicosanoids, bile acid conjugates, and fatty acids, which is consistent with its known function." (PMID 36837791, 2023).
myopathy (continued). "In contrast, known pharmacogenetic variants associated with medication-related adverse events, such as SLCO1B1 increasing statin-related myopathy, were not among the leading associations." (PMID 36653479, 2023). "Since this variant is not linked to atorvastatin-induced myopathy, which is less lipophilic than simvastatin, it's thought that the effects of SLCO1B1 are dependent on the statin type." (PMID 37206522, 2023). "A genetic polymorphism in SLCO1B1, c.521T>C (rs4149056), is associated with a significant reduction in transporter activity, with significantly lower LDL-C reductions and a higher risk of myopathy, especially in homozygous patients." (PMID 34834533, 2021). "SLCO1B1 has been shown to play a relevant role in simvastatin-induced risk of myopathy after increasing the statin’s plasma level, without similarly affecting tolerance to atorvastatin and rosuvastatin." (PMID 34769118, 2021). "In this practical randomized clinical trial, the clinical integration of SLCO1B1 pharmacogenetic testing for simvastatin myopathy risk did not result in poorer measures of ASCVD prevention in routine primary care settings." (PMID 33270123, 2020). "It is clear that although SLCO1B1 is a key risk factor for statin myopathy, it does not explain a significant proportion of the interindividual variability in statin toxicity." (PMID 31220337, 2019). "In detail, the C allele in the T521C SNP of the SLCO1B1 gene and the T allele in the C1236T SNP of the ABCB1 gene exhibit elevated serum CK levels and a higher risk of simvastatin- and rosuvastatin-induced myopathy." (PMID 29296187, 2017). "Taken together these relationships support a hypothesis that inhibition of SLCO1B1 by cerivastatin could be leading to myopathy." (PMID 27161010, 2016). "Consequently, the Clinical Pharmacoenomics Implementation Consortium (CPIP) Guideline for SLCO1B1 and Simvastatin-Induced Myopathy (2012) recommends that prescribing physicians should be alerted to the FDA advice on avoiding high-dose simvastatin." (PMID 27606156, 2016). "Specific SNPs associated with increased risk of statin-induced myopathy (i.e., SLCO1B1 variants) were considered though none were identified in this patient." (PMID 26386973, 2015). "Homozygous carriers of the SLCO1B1 variant had a 16.9 times higher risk for myopathy compared with non-carriers." (PMID 25350695, 2014). "Most strikingly, the SLCO1B1 missense variant c.388A > G resulted in the strongest association with increased OATP1B1 protein expression whereas the c.521T > C variant, linked to statin-related myopathy, did not alter protein levels." (PMID 23311897, 2013). "The purpose of this paper is to assemble evidence relating to the analytical validity, clinical validity and clinical utility of using SLCO1B1 rs4149056 genotyping to inform choice and dose of statin treatment, with the aim of minimising statin-induced myopathy and increasing adherence to therapy." (PMID 24459608, 2013). "It has been validated that polymorphisms in the SLCO1B1 gene, which encodes the protein responsible for hepatic uptake of statins, and the COQ2 gene, which encodes an enzyme involved in the synthesis of coenzyme Q10, are strongly associated with statin-induced myopathy." (PMID 37849732, 2023). "Moreover, the presence of C alleles (TC or CC) within the SLCO1B1 genotype at rs4149056 confers an approximate 3-fold increased risk of clinically adjudicated myopathy independent of non-genetic risk factors." (PMID 34834475, 2021). "Statin-induced myopathy could be justified genetically in certain cases, based on previous findings from the SEARCH genome-wide association study which has identified a SNP in the SLCO1B1 gene as a potential risk factor." (PMID 30050433, 2018). "It is currently unknown whether SLCO1B1 could have utility for predicting lovastatin-induced myopathy because, to our knowledge, SLCO1B1 variation has not been studied for an association with lovastatin-induced myopathy or pharmacokinetics." (PMID 25221728, 2014).